CXCL8 (C-X-C motif chemokine ligand 8)
Diseases named in the same sentence as CXCL8 in open-access papers (continued):
Sharing a sentence is not in itself a finding about the gene and the disease.
glioblastoma (continued). "In glioblastoma, elevated concentration of the chemokine interleukin-8 (IL-8 or CXCL8) has been detected at the tumor resection margin." (PMID 23029099, 2012). "Future investigations, including immunohistochemical staining of HGG and survival analysis based on CXCL8 expression, could offer valuable insights into its potential role in glioblastoma treatment." (PMID 41432874, 2025). "ALKBH5 promotes the expression of the chemokine CXCL8/IL8 in human glioblastoma." (PMID 39726589, 2024). "Also, CXCL8 protein expression was present in the cyst fluid of low-grade astrocytomas, anaplastic astrocytoma, glioblastomas, and oligodendroglioma grade III." (PMID 35269652, 2022). "Glioblastoma cell-secreted CXCL8 induced brain endothelial cell permeability via CXCR2." (PMID 34638514, 2021). "Moreover, it was revealed that this upregulation of CXCL8 in glioblastoma cells induced by Bcl-xL, is mediated through a nuclear factor-kappa B (NF-kB)-dependent mechanism." (PMID 32456359, 2020). "CXCL8 protein expression and its promoter activity in glioblastoma cells may be induced by other pro-tumoral cytokines, such as IL-6 or by anti-apoptotic proteins from Bcl-2 family, such as Bcl-xL." (PMID 32456359, 2020). "It promotes secretion of CXCL8/IL-8 and recruitment of TAMs under anoxic conditions in a glioblastoma multiforme (GBM) model." (PMID 37485079, 2023). "Their polarization is driven by various factors, including osteopontin from mesenchymal-like endothelial cells, glioblastoma stem cell (GSC)-derived signals (e.g., exosomal miR-200c-3p and CXCL8), lactate, and CCL2/CD84–SHP2 signaling." (PMID 40948940, 2025). "In glioblastoma multiforme cells, there was a much greater increase in CXCL8/IL-8 expression compared to CXCL1." (PMID 40427171, 2025). "For example, in glioblastoma, hypoxia-induced ALKBH5 stabilizes SFPQ on the CXCL8 gene by clearing m6A methylated NEAT1, promoting the expression of CXCL8/IL8 and facilitating immune evasion." (PMID 38097948, 2023). "Recently, besides VEGF, an alternative angiogenic signaling pathway via CXCL2/CXCL8 and its receptor CXCR2 was identified as an essential part of angiogenesis in glioblastoma." (PMID 35269652, 2022). "The chemokine genes MIF, CCL2, CXCL8, CX3CL1 and CXCL2 were all highly expressed by the six glioblastoma primary lines." (PMID 36430641, 2022). "Hypoxia can also indirectly increase the expression of CXCL8 in glioblastoma multiforme cells by a HIF-1-dependent increase in the expression of ZNF395, a transcriptional factor that supports the increase in CXCL8 expression." (PMID 33467722, 2021). "GBM patients with high levels of CXCL8 displayed shorter disease-free and overall survival, showing that this chemokine may be a prognostic factor of survival in glioblastoma patients." (PMID 32456359, 2020). "We hypothesized the existence of a proliferative signaling loop involving CXC chemokines (e.g., CXCL1 and CXCL8) and their receptors (e.g., CXCR1 and CXCR2) in glioblastoma growth." (PMID 40362634, 2025). "Studies have revealed that IL-8 (also known as CXCL8)/CXC chemokine receptor 1 and 2 (CXCR1/2, also known as IL8R1/2) signaling contributes to tumor cell proliferation, invasion, and neovascularization of glioblastoma." (PMID 40362634, 2025). "There, genes with a higher expression in glioblastoma compared to astrocytoma were VEGFA, 4EBP1, CCL2, PLAU (uPA), CXCL8 (IL8), CXCL10 (IP10), CASP8, HGF, LIF, CD40, CDCp1, TNFRSF11B (OPG), CD274 (PD-L1), IL6, CXCL1, CCL20 (MIP3α), CCL8 (MCP2), CD244, MMP1, TNFRSF9, CXCL6, MMP10, FGF5)." (PMID 35301393, 2022). "CXCL8 and CXCL2 enhance angiogenesis through CXCR2 signaling on endothelial cells in glioblastoma." (PMID 35011369, 2021). "In glioblastoma multiforme cells, an increase in CXCL8 expression in chronic hypoxia is AP-1-dependent but not NF-κB-dependent." (PMID 33467722, 2021).
glioblastoma (continued). "Thus, we analyzed the U87-CM and identified the chemokine interleukin-8 (IL-8, also known as CXCL8) as the most elevated factor in the glioblastoma secretome." (PMID 23029099, 2012). "Furthermore, we observed a notable increase in the correlation between CXCL8 expression and M2 macrophage infiltration in recurrent glioblastoma, a finding not extensively documented previously." (PMID 41432874, 2025).
pneumonia (139 papers, 2005 to 2025). An acute, acute and chronic, or chronic inflammation focally or diffusely affecting the lung parenchyma, caused by an infection in one or both of the lungs (by bacteria, viruses, fungi, or mycoplasma.). "LTB4, like CXCL-8, is a powerful neutrophil chemoattractant implicated in the pathogenesis of pneumonia." (PMID 29696149, 2018). "Using PCR-DNA sequence verdicts, the TLR2 (354 bp), CLEC4E (443 bp), PTX3 (363 bp), CXCL8 (300 bp), SOCS3 (480 bp) and IL15RA (378 bp) genes were found to have different SNPs in the amplified DNA bases linked to pneumonia." (PMID 40559821, 2025). "Gene expression analysis revealed significant upregulation of immune-related markers (TLR2, CLEC4E, PTX3, CXCL8, IL15RA) and notable SNP variations associated with pneumonia susceptibility." (PMID 40559821, 2025). "Using a novel antibody, nitrated CXCL8 was detected in bronchoalveolar lavage samples from patients with pneumonia." (PMID 36622452, 2023). "CCL2/MCP-1 and CXCL8/IL-8 have been shown to recruit and activate monocytes/macrophages and neutrophils respectively in models of influenza pneumonia, leading to progression to ARDS." (PMID 22022504, 2011). "This underscores the significance of the hyper-inflammatory cell subsets and molecules (CXCL8 and S100A8/A9) as possible therapeutic targets for mitigating the immunopathogenesis seen in severely infected pneumonia patients." (PMID 39757231, 2025). "The genes TLR2, CLEC4E, PTX3, CXCL8, and IL15RA exhibited significantly higher expression levels in pneumonia-affected ewes compared to healthy controls." (PMID 40559821, 2025). "This study used a PCR-DNA sequencing technique to characterize the immunological (TLR2, CLEC4E, PTX3, CXCL8, SOCS3 and IL15RA) genes in ewes with pneumonia and healthy ewes." (PMID 40559821, 2025). "In vivo data also indicated that both pN11R and pG31P significantly relieved LPS-induced pneumonia in mice through decreasing the expression of TNF-α, CXCL8, and IL-1β, and inhibiting neutrophil influx into the lung." (PMID 31988368, 2020). "Hyperactivation of the proinflammatory cytokines IL-6, CXCL8/IL-8, CCL2/MCP-1 and sTNFR-1 was found in pH1N1 pneumonia (2–15 times normal) and in complicated seasonal influenza, but not in milder pH1N1 infections." (PMID 22022504, 2011). "There was sustained activation of the proinflammatory cytokines (IL-6, CXCL8/IL-8, CCL2/MCP-1, sTNFR-1) in severe pH1N1 pneumonia; the CXCL10/IP-10, CXCL9/MIG and IL-17A responses remained largely suppressed during the hospital course." (PMID 22022504, 2011). "Meanwhile, the results of molecular docking also exposed the active ingredients of YPFG could tack a part in modulating the progression of pneumonia via MMP9, CCL2, IL-1B, IL-6, CXCL8, and TNF." (PMID 36285159, 2022). "The CXCL8 and CCL2 cytokines, also known as chemokines, were abundant in all the pneumonia groups." (PMID 34829225, 2021). "Importantly, HuCAL antibody showed the presence of nitrated CXCL8 in BAL samples from patients with pneumonia but not in controls." (PMID 36622452, 2023). "By comparing the hub genes with the top ten genes of pneumonia, we found 5 overlapping genes (IL-1B, IL-6, CXCL8, TNF, and IL-10), which might interpret on how the YPFG exerts a therapeutic effect in some types of pneumonia but not all types of pneumonia." (PMID 36285159, 2022).
cystic fibrosis (127 papers, 2005 to 2026). Autosomal recessive disorder caused by pathogenic variants in the CFTR gene (cystic fibrosis transmembrane conductance regulator), which encodes a chloride and bicarbonate channel expressed in epithelial cells, and follow the diagnosis criteria. "Similar to cystic fibrosis, CXCL8 is associated with induction of bronchoconstriction by stimulation of CXCR1/CXCR2-expressing airway smooth muscle cells, as shown in guinea pigs." (PMID 36725964, 2023). "Elevated levels of pro-inflammatory cytokines and chemokines such as TNF, IL-6 and CXCL8 are associated with several human diseases including cystic fibrosis, pulmonary fibrosis and AIDS." (PMID 20507572, 2010). "While the FOS gene is known to be associated with apoptosis, CXCL8-mediated recruitment and activation of neutrophils is responsible for causing pathogenesis of lower respiratory tract infection and if overproduced, leads to cystic fibrosis." (PMID 36532041, 2022). "Thus, genetic variants in the IL8 (CXCL8) gene have also been proposed to modulate the risk of pulmonary fibrosis in cystic fibrosis." (PMID 24260493, 2013). "ERK1/2 and p38 MAPK are known to regulate production of CXCL8 in cystic fibrosis lung epithelial cells and alveolar macrophages." (PMID 28494003, 2017). "In an in vitro study using hyperinflammatory macrophages from patients with cystic fibrosis, vitamin metabolites have been shown, in high concentrations (e.g., 25(OH)D >100 nmol/L), to down-regulate CXCL8." (PMID 28383493, 2017). "In cystic fibrosis, macrolides improve quality of life and prevent deterioration of lung function, in asthma they reduce sputum CXCL8 levels and improve quality of life and in non-cystic fibrosis bronchiectasis and COPD they reduce exacerbations." (PMID 25148049, 2014). "So it was demonstrated that miR-155, abundantly expressed in the lungs of cystic fibrosis patients, indirectly promotes inflammation by driving hyperexpression of CXCL8, but that miR-17 overexpression in cystic fibrosis airway epithelial cells decreases CXCL8 production." (PMID 36725964, 2023). "Therefore, the CXCL8 level and these transcription factors are crucial for treating cystic fibrosis." (PMID 27351369, 2016). "Excessive CXCL8 might lead to pulmonary inflammation and cystic fibrosis." (PMID 39998235, 2025). "Besides, cystic fibrosis patients suffer from airway hyperresponsiveness, in which CXCL8 may induce increased contraction of airway smooth muscle cells." (PMID 36725964, 2023). "In addition, CXCL8 is crucial in cystic fibrosis, a neutrophil dominant inflammatory disease." (PMID 27351369, 2016).
acute respiratory distress syndrome (123 papers, 2008 to 2026). Progressive and life-threatening pulmonary distress in the absence of an underlying pulmonary condition, usually following major trauma or surgery. "CXCL8 levels, on the other hand, were found to be substantially linked to the severity and pathogenesis of tuberculosis-induced acute respiratory distress syndrome (ARDS)." (PMID 36164329, 2022). "On the other hand, blood CXCL8 levels are strongly associated with the severity of TB-induced acute respiratory distress syndrome (ARDS)." (PMID 37818041, 2023). "NET presence was found to be elevated in acute respiratory distress syndrome (ARDS) patients with ventilator-associated pneumonia compared to ARDS alone, and correlated with both bacterial burden and CXCL8." (PMID 32013006, 2020). "In COVID-19-associated cytokine storms, heightened expression of CXCL10, CXCL8, and CCL2 has been implicated in the pathogenesis of acute respiratory distress syndrome (ARDS)." (PMID 41268545, 2025). "A high expression level of CXCL-8 has been found in pulmonary diseases, including acute respiratory distress syndrome and idiopathic pulmonary fibrosis." (PMID 33329539, 2020). "As it has been shown that CXCL13 and CCL21 have synergistic effects in lymphoid tissue production in RA synovitis and more recently that CCL7 has been shown to synergise with CXCL8 in acute respiratory distress syndrome to promote neutrophil migration." (PMID 28648867, 2017). "As in humans, our model showed neutropenia and elevated IL-8 (CXCL-8) levels, which resulted in massive neutrophil recruitment into the lungs as shown through longitudinal histopathological analysis and consistent with the exudative phase of clinical acute respiratory distress syndrome." (PMID 38149013, 2023). "The resulting acute respiratory distress syndrome (ARDS) and extrapulmonary multi-organ dysfunction are provoked by the excessive production of pro-inflammatory cytokines (IL-6, CXCL8) and chemokines (CXCL10, CCL5, CCL2), a phenomenon also referred as cytokine storm." (PMID 35013790, 2022). "Also, CCL2 and CCL7 chemokines are known to work synergistically with CXCL8 to drive neutrophil trafficking to the lungs during acute respiratory distress syndrome (ARDS)." (PMID 34737734, 2021). "A recent study reported that in acute respiratory distress syndrome (ARDS), CCL2, and CCL7 synergize with CXCL8 to promote neutrophil migration." (PMID 29018439, 2017). "Clinical complications such as acute respiratory distress syndrome (ARDS) also modify the lung microenvironment; it was observed that CXCL8 levels in BALF were significantly higher in an ARDS + TB group compared to TB and ARDS alone groups, although CXCL8 was also increased in both pathologies." (PMID 36009042, 2022).
chronic obstructive pulmonary disease (121 papers, 2005 to 2025). A chronic and progressive lung disorder characterized by the loss of elasticity of the bronchial tree and the air sacs, destruction of the air sacs wall, thickening of the bronchial wall, and mucous accumulation in the bronchial tree. "Additionally, the release of CXCL8 was observed together with IL-1β in cigarette smoker-associated chronic obstructive pulmonary disease (COPD) patients." (PMID 33613529, 2020). "A modest effect targeting CXCL8 with a mAb has been reported in a Phase II clinical trial against chronic obstructive pulmonary disease (COPD)." (PMID 28974038, 2017). "Elevated levels of CXCL8 have been observed in the diseases such as arthritis and chronic obstructive pulmonary disease (COPD)." (PMID 21358586, 2011). "CXCL8 thus plays a role in chronic obstructive pulmonary disease (COPD), neutrophilic asthma, cystic fibrosis, rheumatoid arthritis and other autoimmune diseases, and, moreover, in cancer." (PMID 40124384, 2025). "In HAECs from individuals with chronic obstructive pulmonary disease, WNT4 upregulation increases IL8 and CXCL8 gene expression." (PMID 31558434, 2019). "Therefore, the CXCL8/CXCR2 axis antagonists have been evaluated in clinical trials of various respiratory distress conditions in influenza, eczema, and chronic obstructive pulmonary disease (COPD)." (PMID 36187170, 2022). "Currently, two IL-8 targeting antibodies, ABX-CXCL8 and HuMax-CXCL8, are being used in preclinical studies including patients with severe bronchitis and chronic obstructive pulmonary disease (COPD) (NCT00035828) as well as patients with advanced malignant solid tumors (NCT02536469; NCT03689699)." (PMID 35069554, 2021). "For example, decreased expression of the ARE binding protein AUF-1 in chronic obstructive pulmonary disease (COPD) patient samples leads to stabilization of IL-6, CCL2, CCL1 and CXCL8 mRNA." (PMID 33806254, 2021).
Insulin resistance (114 papers, 2009 to 2026). Increased resistance towards insulin, that is, diminished effectiveness of insulin in reducing blood glucose levels. "Genes such as sirtuin-1 (SIRT1), C-reactive protein (CRP), C-X-C motif chemokine receptor 2 gene (CXCR2), as well as chemokines and interleukins such as interleukin 12 (IL12A) and C-X-C motif chemokine ligand 8 (CXCL8), are strongly associated with insulin resistance and T2D." (PMID 38674857, 2024). "Thus, inflamed adipose tissue could promote low-grade systemic inflammation by releasing proinflammatory cytokines and chemokines (IL-1ß, TNF-α, IL-6, leptin, CCL2, CCL3, and CXCL8) and causing insulin resistance and endothelial dysfunction." (PMID 28512338, 2017). "CXCL8, a major adipocytokine, inhibits insulin-induced protein kinase B (AKT) phosphorylation in adipocytes, contributing to insulin resistance." (PMID 38674857, 2024). "Examination of the KEGG pathway for NAFLD (hsa04932) demonstrated transcriptional dysregulation of mediators of insulin resistance (IRS2, P1K3R1, AKT1), steatohepatitis ( JUN, ERN1) and neutrophil infiltration and inflammation (CXCL8)." (PMID 29786565, 2018). "In parallel, CXCL8 can act in a β cell-autonomous manner, and exert non-immune actions on adipocytes, hepatocytes, podocytes, and muscle cells that contribute to insulin resistance and diabetic complications." (PMID 40718478, 2025).
periodontal disease (108 papers, 2007 to 2026). "CXCL8 is an important chemokine that plays an important role in periodontal disease, since it recruits and activates acute inflammatory cells." (PMID 32867386, 2020). "We focused on the measurements on the expression of IL-6, CXCL8, and CCL2, which are thought to play an important role in the progression of periodontal disease." (PMID 27504628, 2016). "IL-8/CXCL8, a chemoattractant of PMNs, showed a rapid increase in GCF preceding the clinical signs of periodontal disease following cessation of tooth brushing." (PMID 24151615, 2013).
endothelial dysfunction (97 papers, 2013 to 2026). In vascular diseases, endothelial dysfunction is a systemic pathological state of the endothelium (the inner lining of blood vessels) and can be broadly defined as an imbalance between vasodilating and vasoconstricting substances produced by (or acting on) the endothelium. "It was reported that this proinflammatory protein may act on coronary artery disease even endothelial dysfunction and CXCL8 classically associates with an effective angiogenic role." (PMID 34046056, 2021). "Additionally, elevated IL-6 and CXCL8 similarly promote vascular inflammation and endothelial dysfunction, exacerbating microvascular damage despite systemic inflammation control." (PMID 41030257, 2025). "This complex inflammatory stimulus triggers early signs of endothelial dysfunction in HAOEC (i.e., upregulation of CXCL8, CXCR2, and MMP9 genes in the presence of variable MMP9 protein activity) but extracellular matrix/angiogenesis-related changes in HAOSMC." (PMID 41227357, 2025). "Ninj1 silencing in endothelial cells suppressed NF-κB signaling and its key inflammatory mediator CXCL-8, conferring protection against ox-LDL-induced endothelial dysfunction by enhancing proliferation and migration while reducing apoptosis (all p < 0.05)." (PMID 41280941, 2025). "Endothelial Ninj1 silencing was performed to assess its effects on NF-κB signaling, CXCL-8 expression, and ox-LDL-induced endothelial dysfunction." (PMID 41280941, 2025). "Upon recruitment to inflamed endothelium via chemokines such as CXCL1 and CXCL8, neutrophils exacerbate vascular inflammation by releasing pro-inflammatory cytokines, including IL-1β, IL-8, and tumor necrosis factor-α (TNF-α), which amplify endothelial dysfunction and promote monocyte adhesion." (PMID 40217958, 2025).